INS (insulin)
Diseases named in the same sentence as INS in open-access papers (continued):
Sharing a sentence is not in itself a finding about the gene and the disease.
Insulin resistance (continued). "Overexpression of miR-181a levels were found in insulin-resistant cultured hepatocytes, and inhibition of miR-181a may lead to increased protein levels of SIRT1, which is a potential therapeutic target for combating insulin resistance, and thereby improving hepatic insulin sensitivity." (PMID 34006268, 2021). "The fetal insulin hypothesis proposed a possible role for heritable insulin resistance, and there has been evidence for a relationship between low birthweight and higher levels of paternal insulin resistance in case–control (n=119) and cross-sectional (n=2788) studies." (PMID 33569631, 2021). "This suggests that exercise is protective on insulin pathways if it is started before the onset of disease; however, exercise after the onset of severe insulin resistance may be ineffective, only improving insulin secretion for compensation to maintain blood glucose homeostasis." (PMID 34948750, 2021). "However, there are two primary pathological mechanisms responsible for the development of T2D: defective insulin production by pancreatic β-cells and insulin resistance (IR) which arises due to the impaired ability of insulin-sensitive tissues to respond to insulin." (PMID 34690759, 2021). "Therefore, it seems plausible that autophagy could be accelerated in diabetic cardiomyopathy due to the fact of cardiac insulin resistance and impaired insulin signaling in T1D and T2D." (PMID 34831481, 2021). "In addition, insulin resistance is a hallmark of obesity, and it has been suggested that unbalanced lipid metabolism, dysbiosis, chronic inflammation and dysregulation of signaling pathways (insulin route) contribute to the development of the insulin resistance in this disease." (PMID 34208379, 2021). "However, no studies on the relationship between NEFAs, TLR4/NF-κB and the insulin resistance signaling pathway, nor how NEFAs cause insulin resistance in primary calf hepatocytes, have been carried out." (PMID 34966805, 2021). "Therefore, it has been hypothesized that in renal transplant recipients, inflammatory microenvironment could promote the development of peripheral insulin resistance and may lead to impaired insulin secretion in pancreatic β-cells." (PMID 33810367, 2021). "Furthermore, compared with the control, Bacteroides-gavaged mice exhibited significantly decreased systemic glucose intolerance and near-significant improvement in insulin resistance, as revealed by the results of the 1-g oral glucose tolerance test and insulin tolerance test." (PMID 34805797, 2021). "Associations have also been found between increased serum zonulin levels with increased BMI, waist-to-hip ratio, and triglyceride levels, as well as with high fasting insulin levels; thus, it has been proposed that increased zonulin may be related to insulin resistance." (PMID 34960024, 2021). "Because the majority of exercise-induced gene expression changes were not correlated with insulin sensitivity, it can be speculated that obesity, even in the absence of insulin resistance, is sufficient to cause an altered molecular response to exercise." (PMID 33897458, 2021). "Insulin resistance is the inability of the target tissues to orchestrate well-coordinated glucose-lowering processes, including the suppression of gluconeogenesis, lipolysis, net glycogen synthesis, and cellular glucose uptake in response to physiological blood insulin levels." (PMID 34603195, 2021). "This assumption represents an understandable simplification in the absence of further information, but diabetic people are actually known to suffer from reduced insulin sensitivity as well, and avoiding to consider diabetic insulin resistance could lead to misleading results." (PMID 34570804, 2021).
Insulin resistance (continued). "In addition, ChREBP knocked-out mice have worse sensitivity to insulin, so ChREBP is able to dissociate conditions such as hepatic steatosis from insulin resistance and therefore contributes to the maintenance of insulin sensitivity with the counterpart of inducing a fatty liver." (PMID 33946267, 2021). "However, it is unknown if inflammatory triggers act through IRE1 kinase to promote adipocyte insulin resistance, which would then reduce the ability of insulin to suppress lipolysis." (PMID 33610548, 2021). "Insulin producing beta-cells play a central role in the pathogenesis of T2D; the inability of beta-cells to adapt and compensate for increased insulin demand, for example, which develops as a consequence of insulin resistance in ageing or obesity, leads to T2D." (PMID 34436455, 2021). "Insulin resistance and hyperinsulinaemia may predispose women with PCOS to gain weight, supported by insulin therapy-inducing weight gain through anabolic effects of insulin and changes in energy expenditure, glycosuria, and food intake." (PMID 34814919, 2021). "Therefore, the fact that exercise training increases insulin sensitivity but does not consistently decrease circulating BCAA does not necessarily preclude that BCAA are involved in the pathogenesis of insulin resistance, or modulate insulin secretion and clearance." (PMID 33996878, 2021). "Moreover, findings regarding the improvement in insulin sensitivity are confirmed by other experimental results indicating that Mg is able to decrease oxidative stress and inflammatory parameters, two main contributors of insulin resistance." (PMID 34836329, 2021). "The improvement of insulin sensitivity was observed in correlation with lower serum ferritin levels several years ago, and later, it was well documented that the consumption of meat, especially red and processed, favors the development of T2D across increased insulin resistance." (PMID 34205679, 2021). "In animal models of AD, changes in insulin signaling cause memory impairment, while investigations of patients with prediabetes found that insulin resistance, rather than elevation of blood glucose, may cause cognitive decline, especially in the memory domain." (PMID 34576151, 2021). "Similarly, brain insulin resistance is an impairment of brain cells to respond to insulin input." (PMID 34070553, 2021). "Furthermore, the observation that ULT decreased fasting insulin levels in combination with improvement of insulin resistance may suggest that uric acid-lowering agents can ameliorate β-cell function." (PMID 34394285, 2021). "Indeed, a state of insulin resistance may develop as part of the physiologic (pregnancy and lactation) processes, which may manifest as decreased insulin sensitivity." (PMID 34438693, 2021). "However, FFA are typically regarded as the cause of insulin resistance rather than a direct driver of insulin secretion by the β-cell." (PMID 33712379, 2021). "Insulin therapy may be beneficial for endothelial function in patients with type 1 diabetes who have a healthy energy balance without insulin resistance since there is little concern about selective insulin resistance." (PMID 34439553, 2021). "A number of studies have documented Myo’s anti-inflammatory and insulin-sensitizing properties in a variety of experimental models, pointing to a possible significant role for this molecule in modulating molecular pathways leading to inflammation, oxidative stress, and insulin resistance." (PMID 34199095, 2021). "Based on the rationale that effects of insulin on lipolysis occur at lower levels than for glucose metabolism, the TyG index, the product derived from fasting blood glucose and triglyceride levels, has been suggested as a simple alternative surrogate marker of insulin resistance." (PMID 33402193, 2021).
Insulin resistance (continued). "There is also evidence to support genetic links between type 2 diabetes secondary to reduced insulin action and lower birthweight but this applies only to loci implicated in body fat distribution and not those influencing insulin resistance via obesity or lipid metabolism by the liver." (PMID 33569631, 2021). "Indeed, these indices are as reliable as homeostatic model assessment for insulin resistance (HOMA-IR) regarding insulin resistance, but additionally are simpler, easier to interpret, and inexpensive than analyzing insulin or HOMA, as well as more informative than glucose measurements." (PMID 34790686, 2021). "IL-8 impairs insulin action on adipocytes and attenuates insulin-dependent Akt-activation; thus, this insulin-dependent augmentation of palmitate-induced IL-8 formation might worsen insulin resistance in a feed-forward loop." (PMID 33919366, 2021). "The results of its eight-week consumption in 66 NAFLD patients showed that soy milk consumption (240 ml per day) could significantly diminish the level of serum insulin (p=0.04), homeostasis model assessment of insulin resistance (p=0.03), and blood pressure (p=0.04)." (PMID 34426744, 2021). "The metabolites TMAO, carnitine, γ-butyrobetaine, and crotonobetaine may be associated with insulin resistance, and betaine and choline may be associated with greater insulin sensitivity, but temporality of the associations was not established." (PMID 34448864, 2021). "Nasal insulin administration stimulates hypothalamic insulin signaling to suppress hepatic glucose production and enhance insulin sensitivity in lean individuals, while having little effect in the obese, indicating hypothalamic insulin resistance to be the etiology of metabolic disorders." (PMID 33943029, 2021). "Thus, an increase in insulin secretion or β-cell mass can compensate for the insulin resistance by normal β cells, producing more circulating insulin; however, insufficient compensation results in the onset of glucose intolerance, leading to exacerbation of hyperglycaemia." (PMID 34209800, 2021). "It has been hypothesized that TPTD-induced impaired insulin resistance may be due to an increased intracellular free calcium concentration, leading to a decrease in insulin-dependent glucose transport, downregulation of insulin receptors, and increased islet amyloid polypeptide (IAPP) levels." (PMID 33801212, 2021). "Hence, insulin resistance or changes to the GLUT4-insulin cascade could potentially prevent glucose uptake by those tissues that can utilize fat as a source to prioritize the brain and red blood cells." (PMID 33505701, 2021). "Brn-3b is expressed in insulin-responsive metabolic tissues (e.g. skeletal muscle and adipose tissue) and is important for normal function because constitutive Brn-3b-knockout (KO) mice develop profound metabolic dysfunction (hyperglycaemia; insulin resistance)." (PMID 33712567, 2021). "Interestingly, insulin resistance and β-cell function are inversely correlated with thyroid-stimulating hormone which may be explained by insulin-antagonistic effects of thyroid hormones along with an increase in TSH." (PMID 33099763, 2021). "Indeed, the disturbed fat storage into WAT observed in lipodystrophies, obesity, or insulin resistance leads to the ectopic accumulation of fat in other tissues such as skeletal muscle, liver, pancreas, driving the insulin resistance or dysfunction in these tissues." (PMID 33435513, 2021). "Replacing fasting insulinemia with other parameters of insulin-resistance/sensitivity e.g. (M-value/Insulin r2=0.571; p=0.031) or area under the insulinemic curve (oGTT) (r2=0.599; p=0.003) revealed, that both could explain some of the variability in serum afamin concentration." (PMID 34603196, 2021).
Insulin resistance (continued). "Most of the genetic associations have been ascribed to β-cell function and very few have been linked to insulin resistance, although this may be partly because no good measures of insulin sensitivity are available in large cohorts." (PMID 33387681, 2021). "VD3 was shown to enhance insulin synthesis and release, increase insulin receptor expression and inhibit the production of proinflammatory cytokines that might counteract the development of insulin resistance." (PMID 33095902, 2021). "Moreover, chitosan supplementation could also reduce the concentration of TNF-α, which might improve insulin resistance, thereby reducing insulin secretion." (PMID 34443619, 2021). "On the basis of insulin secretion deference, we suspected that the insulin signaling pathway (insulin resistance and reduced glucose utilization), such as phosphoinositide 3-kinase (PI3K)/protein kinase B (AKT) signaling, could be involved in inducing differential protein changes in retinal tissue." (PMID 34725563, 2021). "In addition, 1/2Nx was found to increase insulin sensitivity, whereas uremic conditions reduce this sensitivity, in Wistar rats, suggesting that reduced gluconeogenesis capacity resulted from the partial improvement in insulin resistance induced by 1/2Nx." (PMID 34356489, 2021). "An increase in these cytokines can impair insulin signaling in the adipocyte, leading to a decrease in insulin-mediated glucose uptake and lipid accumulation, and increase ectopic lipid accumulation, which eventually exacerbates insulin resistance and can even lead to T2DM." (PMID 33705353, 2021). "In this context, it may seem ‘paradoxical’ that the over-expression of antioxidant enzymes leads to the development of insulin resistance in mice, and that growth factors such as insulin stimulate the generation of localised ROS, which play a role in facilitating downstream insulin signalling." (PMID 33893069, 2021). "Interestingly, central infusion of ketone bodies potentiated leptin and insulin brain signaling (possibly affecting food intake) and directly improved hepatic insulin sensitivity, suggesting effects on insulin resistance, independent of weight loss." (PMID 33444495, 2021). "HFD-fed Mgl2-DTR mice treated with diphtheria toxin showed weight loss, enhanced insulin sensitivity and gluconeogenesis, accompanied by a marked reduction in circulation of RELM α, a multifunctional cytokine produced by mononuclear phagocytes with roles in promoting insulin resistance and obesity." (PMID 33829022, 2021). "Similarly, red raspberry intake with a high carbohydrate breakfast meal reduced postprandial glycaemia and the concomitant insulin demand in overweight or obese individuals with pre-diabetes and insulin resistance across time frames that anthocyanin and phenolic metabolites were apparent in blood." (PMID 32747995, 2021). "In addition, a low concentration of DHEA-S in serum could lead to insulin resistance, while high insulin concentrations could down-regulate the concentration of DHEA-S by inhibiting promotion and producing its clearance." (PMID 34771066, 2021). "Therefore, the endothelial cell IR knockout mouse (VENIRKO) showed normal glucose homeostasis and normal vascular development, but altered ET-1 and eNOS expression, vascular insulin resistance and a modest alteration in the regulation of blood pressure and insulin sensitivity under a low-salt diet." (PMID 34440804, 2021). "MDP-stimulated insulin resistance was associated with increased inhibitory serine phosphorylation of insulin receptor substrate-1 (IRS-1) and reduced activating IRS-1 tyrosine phosphorylation, as well as decreased GLUT4 translocation and insulin-stimulated glucose uptake." (PMID 33503814, 2021).
Insulin resistance (continued). "One vital metabolic adaptation relates to insulin sensitivity: as pregnancy progresses, gradual rises in gestational hormones (including estrogen, progesterone, prolactin, cortisol, placental growth hormone and human placental lactogen) promote a state of persistent insulin resistance." (PMID 34073737, 2021). "Zn deficiency is reported to impair glucose metabolism and disturb metabolic adaptation to meal-feeding in rats, thereby increasing insulin resistance, which may correlated with differences in the effect of insulin on glucose uptake and metabolism in these tissues." (PMID 33661932, 2021). "Hence, once the hepatic insulin signaling cascade faces impairment resulting in hepatic insulin resistance, other metabolic symptoms occur, incurring hyperglycemia, inflammation, and de novo lipogenesis, and further, hepatic steatosis and nonalcoholic fatty liver disease (NAFLD)." (PMID 34603195, 2021). "In order to investigate whether an improvement in insulin resistance could be achieved after the two diets, we compared elicited effects on insulin and HOMA-IR variation using linear mixed effect regression models, with adjustment for treatment period and intervention sequence." (PMID 34959931, 2021). "Insulin resistance might contribute to hyperandrogenism by several mechanisms: insulin acts synergistically with luteinizing hormone to improve androgen production, and high levels of insulin reduce circulating SHBG levels, thereby increasing the bioavailability of testosterone." (PMID 34081616, 2021). "Or, it could be possible that corticosterone‐driven insulin resistance could increase plasma glucose which would then stimulate the release in insulin, and that this could be modulated by AR blockade." (PMID 33393733, 2021). "As insulin treatment may promote weight gain in people with T2DM and T1DM, this creates a vicious cycle in this population; where overweight/obesity will result in the need for more insulin to overcome insulin resistance, whilst injecting more insulin would promote weight gain." (PMID 34530819, 2021). "Dysregulation of ECM remodelling via elevated TGFβ ligands and inflammation results in excess collagen deposition, which may create a physical barrier that could impair the uptake of glucose and the binding of insulin to the receptor, contributing to the development of insulin resistance." (PMID 34707569, 2021). "Currently, we demonstrated previously that IH induces hyperinsulinemia and associated altered insulin signaling in adipose tissue, liver, and skeletal muscle, but the impact of IH‐induced insulin resistance on cardiac insulin signaling and functional/structural cardiac consequences remains unknown." (PMID 33682327, 2021). "Salt intake has a close relationship with hypertension and may be a determinant of the pathogenetic link between salt sensitivity and insulin resistance, because it impairs insulin sensitivity in normotensive and hypertensive patients with salt sensitivity but not in those with salt resistance." (PMID 34966295, 2021). "Notably, dietary fat may play a vital role in the development of insulin resistance, inhibiting insulin-stimulated glucose uptake by a physiological increase in plasma free fatty acid or altering the enzyme activity and gene expression." (PMID 33661377, 2021). "Thus, the increased supply of energy substrates and the inflammatory environment under T2D conditions are thought to result in the excessive generation of mitochondria-derived ROS that suppress the insulin signalling cascade and thereby promote the development of insulin resistance." (PMID 33893069, 2021). "However, even though participants were normoglycemic, the PAE of exercise on insulin sensitivity was inversely related to baseline insulin sensitivity, which raises the possibility that less might be needed for individuals with insulin resistance." (PMID 34386716, 2021).